RN7SL448P (RNA, 7SL, cytoplasmic 448, pseudogene)
Gene: Miscellaneous RNA gene on chromosome 17 (60,899,891 to 60,900,185, forward strand). Ensembl gene ENSG00000264322.
Homologues: Orthologues: chimpanzee Metazoa_SRP (99% identical), macaque Metazoa_SRP (93% identical). Paralogues in human: RN7SL3 (87% identical), RN7SL1 (87% identical), RN7SL2 (87% identical), RN7SL18P (84% identical), RN7SL220P (84% identical), RN7SL91P (84% identical), RN7SL126P (84% identical), RN7SL664P (84% identical), RN7SL709P (84% identical), RN7SL147P (83% identical), RN7SL478P (83% identical), RN7SL566P (83% identical), and 707 more.